MIR5006 (microRNA 5006)
Synonyms: hsa-mir-5006
Gene: MicroRNA gene on chromosome 13 (41,568,286 to 41,568,395, reverse strand). Ensembl gene ENSG00000284584.
Homologues: Orthologues: chimpanzee MIR5006 (100% identical).